TAGLN2 (transgelin 2)
Diseases named in the same sentence as TAGLN2 in open-access papers (continued):
Sharing a sentence is not in itself a finding about the gene and the disease.
lymph node metastasis (7 papers, 2011 to 2025). "High expression of CXCR7 and TAGLN2 was significantly associated with lymph node metastasis, as determined by Fisher’s exact test." (PMID 41169389, 2025). "The significant association of CXCR7 and TAGLN2 with lymph node metastasis underscores their clinical relevance in the context of aggressive PTC." (PMID 41169389, 2025). "Transgelin-2 has been linked to lymph node metastasis, advanced clinical stage, and survival of cancer patients." (PMID 28521289, 2017). "The level of transgelin-2 was significantly associated with lymph node metastasis, histological grade, and tumor stage and size." (PMID 28521289, 2017). "Furthermore, elevated expression levels of CXCR7 and TAGLN2 were significantly associated with lymph node metastasis in PTC patients (CXCR7, p < 0.05; TAGLN2, p < 0.05; R = 0.353), providing strong evidence for their involvement in PTC progression." (PMID 41169389, 2025). "High expression of both proteins was significantly associated with lymph node metastasis in PTC patients, and a significant positive correlation was observed between CXCR7 and TAGLN2 expression levels." (PMID 41169389, 2025). "Our results demonstrate that both CXCR7 and TAGLN2 are markedly overexpressed in PTC tissues, and high expression levels of these proteins are strongly associated with lymph node metastasis, a key prognostic indicator." (PMID 41169389, 2025). "In the present study, lymph node metastasis, histological grade, and tumor stage and size were closely related to the level of transgelin-2 in PDAC." (PMID 28521289, 2017). "High expression of CXCR7 and TAGLN2 was significantly associated with lymph node metastasis (p < 0.05), but not with other clinicopathological parameters, including age, sex, tumor size, capsular invasion, or multifocality." (PMID 41169389, 2025). "In addition, TAGLN2 overexpression has been reported to be correlated to lymph node metastasis and histological neural invasion of bladder, colorectal, esophageal, and gastric cancer." (PMID 29110682, 2017). "Given that lymph node metastasis is a well-established predictor of adverse prognosis in PTC, these findings underscore the clinical relevance of CXCR7 and TAGLN2 and suggest their potential utility as prognostic biomarkers." (PMID 41169389, 2025). "CXCR7 and TAGLN2 are overexpressed in PTC and correlate closely with lymph node metastasis." (PMID 41169389, 2025).
ovarian carcinoma (7 papers, 2013 to 2025). A malignant neoplasm originating from the surface ovarian epithelium. "CAR-T cells overexpressing TAGLN2 bypass ER stress and show improved therapeutic efficacy in ovarian cancer models." (PMID 40624498, 2025). "TAGLN2 is found to be an important protein in the ovarian cancer microenvironment by cytoskeletal organization." (PMID 38918474, 2024). "In this study, we confidently identified the marker combination of EEF1G + MSLN + BCAM + TAGLN2 which showed upregulation in both serum and tissue an outperforming marker panel against currently available markers for ovarian cancer." (PMID 38918474, 2024). "Analysis of ovarian cancer specimens revealed that endoplasmic reticulum (ER) stress responses elicited by the tumor microenvironment repress TAGLN2 in infiltrating CD8+ T cells, enforcing their dysfunctional state." (PMID 38168227, 2023). "Tumour-induced ER stress suppresses TAGLN2, impairing T cell function in ovarian cancer." (PMID 40624498, 2025). "Ovarian Cancer: In ovarian cancer, FABP5 interacts with TAGLN2, promoting TAGLN2 cell surface localization and its role in activated CD8 + T cells." (PMID 40717587, 2025). "By overexpressing TAGLN2 in CAR T-cells to circumvent stress responses and maintain CAR T-cell fitness, they demonstrated that TAGLN2-armored CAR T-cells improved control of metastatic disease progression and survival of mouse models of ovarian cancer." (PMID 41019052, 2025). "In endometrial and ovarian cancers, western blotting revealed that the expression of alpha-enolase (ENO1) and triosephosphate isomerase (TPI-1) was higher and the expression of Transgelin-2 (TAGLN2) was lower in metastatic tumors than in primary tumors." (PMID 23504277, 2013).
pancreatic cancer (7 papers, 2011 to 2025). "Moreover, transgelin-2 partially rescued the growth defect of pancreatic cancer cells caused by SREBP-1 knockdown, suggesting that transgelin-2 is required for SREBP-1-mediated cell growth upon insulin treatment." (PMID 28521289, 2017). "Our results provide a novel mechanism of KRAS addiction in PDAC and link the ability of mutant KRAS to promote pancreatic cancer cell proliferation with transgelin-2." (PMID 30041673, 2018). "In previous reports, we have shown increased expression of transgelin-2 in pancreatic cancer tissues compared with adjacent normal tissues." (PMID 30041673, 2018). "Up-regulation of transgelin-2 was observed in pancreatic cancer, colorectal cancer, lung adenocarcinoma and cervical squamous cell carcinoma." (PMID 30041673, 2018). "Of the 114 pancreatic cancer samples, 61 (54%) strongly expressed S145 phosphorylation of transgelin-2 and these patients had a median survival of only 9 months compared with 33 months in the 53 (46%) patients with weak staining (p = 0.004)." (PMID 30041673, 2018). "We found that the level of transgelin-2 was significantly higher in KRAS G12 mutant pancreatic cancer cell lines than in wild-type or other types of KRAS (G13D, Q61R, I171M, A146T, etc.)." (PMID 30041673, 2018). "Overexpression of TAGLN2 was observed in HCC and pancreatic cancer." (PMID 21304530, 2011).
metastatic disease (6 papers, 2013 to 2025). "The coordinated overexpression of CXCR7 and TAGLN2, along with their association with metastatic disease, implies a synergistic role in promoting PTC invasion and metastasis, rather than independent contributions." (PMID 41169389, 2025). "Strikingly, however, treatment with TAGLN2-overpressing CER T cells significantly prolonged the overall survival of mice with metastatic disease." (PMID 38168227, 2023). "Consistently, transgelin-2 was found to be more downregulated in metastatic tumors than in primary cancers." (PMID 33731208, 2021). "On the other hand, the expression of TPI-1 and TAGLN2 was lower in metastatic tumors than in primary tumors in cervical cancer." (PMID 23504277, 2013). "Indeed, transgelin-2 is downregulated in metastatic tumors compared with primary cancers, suggesting that transgelin-2 is a suppressor of metastasis." (PMID 33898417, 2021). "However, the expression of TAGLN2 was lower in metastatic tumors than in primary tumors; this finding was consistent with the reported role of TAGLN2 as a tumor suppressor." (PMID 23504277, 2013). "In this study, expression of TPI-1 and ENO1, which enhances cancer cell survival and proliferation, were higher in metastatic tumors than in primary tumors, and TAGLN2, which suppresses invasion of cancer cells, was lower in metastatic tumors than in primary tumors." (PMID 23504277, 2013). "In the present study of clinical tumor samples, we identified the expression of TAGLN2 in primary tumors and we also identified TPI-1 and ENO1 in metastatic tumors, predominantly by LC–MS/MS." (PMID 23504277, 2013). "Further, in cervical cancer, the expression of TAGLN2 and TPI-1 was lower in metastatic tumors than in primary tumors." (PMID 23504277, 2013).
asthma (5 papers, 2020 to 2023). "However, transgelin-2 cannot be a COVID-19 prognostic biomarker because its high levels are also associated with other diseases such as asthma, type 2 diabetes, or cancer." (PMID 37762413, 2023). "In the lung, transgelin-2 has been found to be involved in reducing pulmonary resistance in asthma by airway muscle cell relaxation." (PMID 37762413, 2023). "Based on this situation, this study efficiently screened potential active compounds targeting transgelin-2 and predicted the biological functions and signaling pathways for anti-asthma effects." (PMID 37711178, 2023). "A recent study reported a new function of transgelin-2 in the pathogenesis of asthma, revealing transgelin-2 as a therapeutic target for asthmatic pulmonary resistance." (PMID 33898417, 2021). "Transgelin-2, a smooth muscle marker, is a unique actin-binding protein involved in asthma and cancer." (PMID 32727619, 2020). "Our previous studies showed that transgelin-2 is a new therapeutic target for asthma." (PMID 35784706, 2022). "Based on our results, metallothionein-2 and other transgelin-2 agonists may have therapeutic effects on asthma." (PMID 35784706, 2022). "Our previous study showed that inhaled transgelin-2 agonist, TSG12, effectively reduced pulmonary resistance in a mouse model of asthma in a dose-dependent manner." (PMID 35784706, 2022). "Besides transgelin-2, some targets (i.g., ESR1, EGFR, CASP3, and SRC) may be important for the anti-asthmatic effect of glycyrrhizin, and some signaling pathways (i.g., SRC/EGFR signaling pathway) are also promising research directions for improving asthma." (PMID 37711178, 2023).
esophageal cancer (5 papers, 2023 to 2025). A primary or metastatic malignant neoplasm involving the esophagus. "A study has demonstrated that the aberrant expression of squamous epithelial heat shock protein 58 (Cornulin, CRNN) and transgelin 2 (TAGLN2) is associated with the progression of esophageal precancerous lesions to esophageal cancer." (PMID 40018789, 2025). "Quercetin therapy could reduce growth and invasion but increase cell apoptosis while upregulating miR-1-3p expression and downregulating TAGLN2 expression in oesophageal cancer." (PMID 39457531, 2024). "Further research and functional studies are warranted to fully understand the roles of TAGLN2 and CRNN in esophageal cancer development and progression." (PMID 37553345, 2023). "The results revealed that TAGLN2 was broadly expressed in various cancer types, with significantly increased expression especially in tumor tissues of GBM (Glioblastoma Multiforme), CHOL (Cholangiocarcinoma), and ESCA (Esophageal Carcinoma) compared to normal tissues." (PMID 37553345, 2023).
head and neck squamous cell carcinoma (5 papers, 2011 to 2015). A squamous cell carcinoma that arises from any of the following anatomic sites: lip and oral cavity, nasal cavity, paranasal sinuses, pharynx, larynx, and salivary glands. "In addition, miR-1 also targets TAGLN2 in head and neck squamous cell carcinoma (HNSCC)." (PMID 25874496, 2015).
Alzheimer disease (3 papers, 2023 to 2025). A progressive, neurodegenerative disease characterized by loss of function and death of nerve cells in several areas of the brain leading to loss of cognitive function such as memory and language. "Also, transgelin-2 has been suggested recently to be a potential biomarker for Alzheimer's disease, which is another neuron degenerative disease." (PMID 37324545, 2023). "Through this analysis, we identify three understudied proteins—Tagln2, Slc25a3, and Pafah1b3—that may contribute to the differential sensitivity of Wistar Han rats and C57BL/6 mice to STZ-icv and may play a role in the development and progression of Alzheimer’s disease." (PMID 40450637, 2025).
cholangiocarcinoma (3 papers, 2023 to 2025). A carcinoma that arises from the intrahepatic biliary tree (intrahepatic cholangiocarcinoma) or from the junction, or adjacent to the junction, of the right and left hepatic ducts (hilar cholangiocarcinoma). "The present study demonstrated that serum TAGLN2 levels significantly increased in patients with cholangiocarcinoma." (PMID 38509504, 2024). "TAGLN2 suppression inhibited cancer cell proliferation and reduced resistance to conventional anti-cancer drugs; therefore, TAGLN2 can be applied to most patients with cholangiocarcinoma, suggesting that it is a novel therapeutic target with fewer off-target effects." (PMID 38509504, 2024). "Furthermore, the IF of CAF derived from patients with cholangiocarcinoma confirmed the expression of TAGLN2 in CAFs." (PMID 38509504, 2024).
endometriosis (3 papers, 2014 to 2025). The growth of functional endometrial tissue in anatomic sites outside the uterine body. "It was reported that TAGLN2 is expressed in uterine luminal epithelium, glandular epithelium, endometrial and embryonic implantation sites and that it participates in the regulation of embryo development and the occurrence, invasion, metastasis and differentiation of endometriosis." (PMID 24959893, 2014).
lung adenocarcinoma (3 papers, 2011 to 2022). A carcinoma that arises from the lung and is characterized by the presence of malignant glandular epithelial cells. "A previous publication has identified that TAGLN2 was upregulated in patients with lung adenocarcinoma, most of whom were in the early stage of lung adenocarcinoma." (PMID 35869490, 2022). "In other human cancers such as lung adenocarcinoma, the expression of transgelin-2 has been reported." (PMID 31315664, 2019).
melanoma (3 papers, 2021 to 2023). A malignant, usually aggressive tumor composed of atypical, neoplastic melanocytes. "Tagln2−/− DCs exhibited significant defects in their abilities to home to draining LNs and to form optimal contacts with cognate CD4+ T cells to prime T cells, and these changes were associated with a failure to suppress tumor growth and metastasis of B16F10 melanoma cells in mice." (PMID 33731208, 2021).
papillary thyroid cancer (3 papers, 2021 to 2025). "Crucially, our experiments revealed that knockdown of TAGLN2 in thyroid papillary carcinoma cells led to a significant decrease in p-Smad2 levels, indicating an attenuation of TGF-β signaling activation." (PMID 41169389, 2025). "To evaluate the clinical prognostic significance of CXCR7 and TAGLN2 in PTC, we performedKaplan-Meier survival analysis on the TCGA thyroid papillary carcinoma (PTC) patient cohort." (PMID 41169389, 2025).
prostate carcinoma (3 papers, 2012 to 2019). A carcinoma that arises from epithelial cells of the prostate gland. "E, Differential gene and pseudogene expression for tumor and normal samples for each member of the CNN2/TAGLN2 PGG family in the prostate cancer TCGA dataset." (PMID 31029062, 2019). "As a result, parent genes HTR7, CNN2, MSN, and TAGLN2 are DE; they generate pseudogenes, which are specifically expressed in prostate cancer samples." (PMID 31029062, 2019).
type 2 diabetes (3 papers, 2017 to 2023). "We have previously identified that transgelin-2 is highly expressed in PDAC patients with type 2 diabetes." (PMID 30041673, 2018). "Transgelin-2 is also associated with nonalcoholic fatty liver disease (NAFLD), type 2 diabetes and hyperlipidemia." (PMID 30041673, 2018). "We studied the expression profile of transgelin-2 in both db/db and ob/ob mouse type 2 diabetes model, which display a hyperinsulinemia phenotype." (PMID 28521289, 2017).
colon cancer (2 papers, 2017 to 2025). "Further, the actin-binding protein Tagln2 was suggested as a diagnostic biomarker of HCC as it is overexpressed in 69% of patients and was described to be a target of TGF-β/Smad4 in colon cancer cells." (PMID 28994702, 2017).
COVID-19 (2 papers, 2022 to 2023). A disease caused by infection with severe acute respiratory syndrome coronavirus 2. "Thus, it is possible that transgelin-2 has a significant role in lung function in COVID-19 patients." (PMID 37762413, 2023).
gastric tumor (2 papers, 2021 to 2024). "In this study, Tagln2 expression was significantly upregulated in ECs from gastric tumor tissues compared with that from normal tissues, and significantly correlated with the presence of lymph node as well as distant metastases." (PMID 34150622, 2021). "In conclusions, we demonstrated that Tagln2 expression was significantly upregulated in ECs from gastric tumor tissues compared with ECs from normal tissues and was significantly correlated with the presence of lymph node as well as distant metastases." (PMID 34150622, 2021).
gynecological cancers (2 papers, 2013 to 2023). "At last, we tested TAGLN2 expression and function in UCEC, which is a gynecological malignant tumor with a low survival rate and poor prognosis." (PMID 37476180, 2023).
leukemia (2 papers, 2021 to 2024). A malignant (clonal) hematologic disorder, involving hematopoietic stem cells and characterized by the presence of primitive or atypical myeloid or lymphoid cells in the bone marrow and the blood. "Interestingly, some leukemia and lymphoid tumor cells, such as MEC1 (B-cell chronic lymphocytic leukemia) and Raji (B-cell Burkitt’s lymphoma), express high levels of transgelin-2." (PMID 33898417, 2021).
lupus (2 papers, 2017 to 2025). "Transgelin 2 (TAGLN2) blocks actin depolymerization and was upregulated on activated B cells in lupus patients." (PMID 41259806, 2025). "In support of this, lymph nodes (LNs) from patients with systemic lupus erythematosus (SLE), in which the intense GC activity have been recognized, showed increased TAGLN2 expression in B-cells compared to control LNs." (PMID 28910360, 2017).
lymphoma (2 papers, 2021 to 2024). A malignant (clonal) proliferation of B- lymphocytes or T- lymphocytes which involves the lymph nodes, bone marrow and/or extranodal sites. "Unlike metastatic spread of other cancers, because lymphoma dissemination generally conserved physiological behavior reflecting basic rules of lymphocyte homing, it will be worth investigating whether lymphomas with high transgelin-2 has increased tissue-specific dissemination." (PMID 33898417, 2021).
ovarian tumors (2 papers, 2023 to 2025). "Interestingly, PD-1 blockade did not boost the therapeutic effects of CER-TAGLN2 T cells, leading the authors to conclude that TAGLN2 silencing impaired the ability of CER T cells to control advanced ovarian tumors." (PMID 39948077, 2025).
pulmonary arterial hypertension (2 papers, 2021 to 2025). Pulmonary arterial hypertension (PAH) is a group of diseases characterized by mean pulmonary artery pressure >20 mmHg and elevated pulmonary arterial resistance leading to right heart failure. "This study systematically explored the upstream and downstream mechanisms of the TAGLN2 gene regulated by DNA methylation and its succinylation modification in the pathogenesis of pulmonary arterial hypertension (PAH) by integrating Mendelian randomization and mediation analysis." (PMID 41189171, 2025). "Here, we identified 532 DEPs; several of these DEPs may be critical to CMS or pulmonary hypertension, including α-1-acid glycoprotein, collagen, fibulin, haptoglobin, PLTP, and TAGLN2." (PMID 34471201, 2021).
pulmonary fibrosis (2 papers, 2022 to 2023). Chronic progressive interstitial lung disorder characterized by the replacement of the lung tissue by connective tissue, leading to progressive dyspnea, respiratory failure, or right heart failure. "TAGLN2 was identified as a biomarker in the development of pulmonary fibrosis since it triggered the activation of the TGF-beta/Smad3-pathway." (PMID 38322285, 2023).
Achalasia (1 paper, 2023). A disorder of esophageal motility characterized by the inability of the lower esophageal sphincter to relax during swallowing and by inadequate or lacking peristalsis in the lower half of the body of the esophagus. "In this study, 164 serum proteins changed significantly in achalasia patients among which the most significantly changed proteins were profilin-1, immunoglobulin heavy variable 3–9, transgelin-2, vasodilator-stimulated phosphoprotein, and galectin-10 (all were upregulated)." (PMID 37324545, 2023).
autoimmune disease (1 paper, 2021). A disorder resulting from loss of function or tissue destruction of an organ or multiple organs, arising from humoral or cellular immune responses of the individual to their own tissue constituents. "However, this CpG site is also an eQTM for five other genes in CD4+ T cells (TAGLN2, SLAMF8, DUSP23, PHYIN1 FCRL6), several of which have established autoimmune disease connections." (PMID 34946847, 2021).